IL10 (interleukin 10)
Diseases named in the same sentence as IL10 in open-access papers (continued):
Sharing a sentence is not in itself a finding about the gene and the disease.
overlap syndrome (1 paper, 2023). "Overlap syndrome was associated with increased levels of the CCL11 and CD40 ligands, as well as decreased IL-10 levels." (PMID 36769452, 2023).
vasculopathy (1 paper, 2018). "Thus, systemic and local cytokine productions could be initiated and damage the CNS together with possible vasculopathy in the brain, as researchers have reported elevation of tumor necrosis factor-α, interleukin-6 (IL-6), and IL-10 in CSF in SLE patients." (PMID 29449817, 2018).
IL10 also shares sentences with these, for which no sentence is quoted: chronic periodontitis (40 papers); multiple myeloma (24); acute myocardial infarction (20); viral diseases (11); colon (7); Hypoalbuminemia (7); Parkinsonism (7); acute myocarditis (5); primary open-angle glaucoma (5); rhinosinusitis (5); age (4); alcohol (4); Anorexia (4); carotid atherosclerosis (4); lipid metabolic disorders (4); Myelopathy (4); neuromyelitis optica (4); oral lichen planus (4); polyendocrinopathy (4); polymyositis (4); portal hypertension (4); acute bronchiolitis (3); Acute hepatitis (3); aggressive periodontitis (3); autoimmune lymphoproliferative syndrome (3); Blindness (3); bronchitis (3); dermatomyositis (3); hemophilia (3); hyperhomocysteinemia (3).
A further 366 diseases each share a sentence with IL10 in 3 papers or fewer.